TTPAL (alpha tocopherol transfer protein like)
Description:
May act as a protein that binds a hydrophobic ligand.
Synonyms: C20orf121; dJ179M20.3
Tractability: PROTAC: ubiquitination databases record sites on it; its protein half-life has been measured.
Gene: Protein-coding gene on chromosome 20 (44,470,527 to 44,494,604, forward strand). Ensembl gene ENSG00000124120.
Subcellular location (Human Protein Atlas): Cytosol; Golgi apparatus
Gene Ontology:
Molecular function: phosphatidylinositol bisphosphate binding; phosphatidylinositol-3,5-bisphosphate binding
Cellular component: membrane; trans-Golgi network membrane
Genetic constraint (gnomAD): Loss-of-function variants: 19 observed, 27.7 expected, observed/expected ratio (o/e) 0.69, 90% interval 0.48 to 1.01. The upper end of that interval is the gene's LOEUF score, 1.01, which puts it in group 4 of 6, group 1 being the genes least tolerant of losing a copy. Missense variants: 318 observed, 391.29 expected, observed/expected ratio (o/e) 0.81, 90% interval 0.74 to 0.89. Synonymous variants: 157 observed, 163.6 expected, observed/expected ratio (o/e) 0.96, 90% interval 0.84 to 1.1.
Homologues: Orthologues: chimpanzee TTPAL (99% identical), macaque TTPAL (99% identical), guinea pig TTPAL (95% identical), dog TTPAL (95% identical), mouse Ttpal (94% identical), rat Ttpal (93% identical), pig TTPAL (92% identical), rabbit TTPAL (90% identical), tropical clawed frog ttpal (69% identical), zebrafish ttpal (64% identical), Drosophila melanogaster CG10237 (29% identical). Paralogues in human: CLVS1 (32% identical), CLVS2 (32% identical), RLBP1 (28% identical).
Diseases named in the same sentence as TTPAL in open-access papers:
TTPAL is named in the same sentence as 12 diseases in open-access papers, as found by Europe PMC text mining. Sharing a sentence is not in itself a finding about the gene and the disease. The quoted sentences say what the papers report.
colorectal cancer (4 papers, 2021 to 2025). A primary or metastatic malignant neoplasm that affects the colon or rectum. "For instance, studies have demonstrated involvement of ARRB1, MGST1, and TTPAL in colorectal cancer, leading to increased cancer cell proliferation and subsequent poor prognosis." (PMID 40186098, 2025). "The presented study analysed the expression of CDH1, PTEN, FHIT, and TTPAL genes using tissue samples and blood of patients with different stages of colorectal cancer (CRC)." (PMID 36161592, 2022). "The main aim of the study is to assess expression levels of CDH1, FHIT, PTEN, and TTPAL genes in tumors and peripheral bloods of colorectal cancer patients in staged I–IV." (PMID 36161592, 2022). "TTPAL activates Wnt by stabilizing TRIP6/ β- Catenin signal promotes colorectal cancer." (PMID 38054820, 2023). "“Analysis of copy number of TTPAL in cancers from TCGA studies demonstrated that TTPAL was preferentially and more frequently amplified in colorectal cancers as compared with other cancer types, suggesting its particular involvement in colorectal cancer”." (PMID 36161592, 2022). "Using whole genome sequencing we identified that tocopherol alpha transfer protein-like (TTPAL), located at 20q13.12, was amplified in colorectal cancer." (PMID 34642500, 2021). "Although related expression levels in tissue did not correlate with its expression in blood, consistent with previous studies FHIT and TTPAL genes upregulation and CDH1 downregulation, in especially tumoral tissues, may serve as predictive determinants for the patients with colorectal cancer." (PMID 36161592, 2022).
gastric cancer (4 papers, 2022 to 2025). A primary or metastatic malignant neoplasm involving the stomach. "Previous studies have demonstrated that TTPAL promotes gastric cancer progression through AKT pathway activation." (PMID 40713894, 2025). "Subsequent mechanistic studies revealed TTPAL’s capacity to drive gastric cancer progression via AKT pathway activation." (PMID 40713894, 2025). "Co-IP and confocal immunofluorescence experiments showed that NNMT interacted and co-localized with alpha-tocopherol transfer protein-like (TTPAL), which was upregulated and correlated with poor survival in gastric cancer." (PMID 35338115, 2022). "Recent studies have also focused on tumor promotion in gastric cancer and potential targets for treatment, including MGST1, TTPAL, FBXO11, and IL2RG." (PMID 40186098, 2025). "Overexpression of TTPAL in gastric cancer cells upregulated NNMT, indicating that TTPAL stabilized NNMT in the PI3K/AKT signaling pathway." (PMID 35338115, 2022).
esophageal cancer (1 paper, 2025). A primary or metastatic malignant neoplasm involving the esophagus. "To identify the function of TTPAL in ESCC progression, we first found that TTPAL mRNA levels were significantly higher in tissues of patients with esophageal cancer than in normal tissues in TCGA cohort." (PMID 40713894, 2025). "Consistent with in vitro results, simvastatin treatment showed better therapeutic efficacy in nude mice bearing subcutaneous esophageal cancer xenografts without TTPAL knockdown compared to those with TTPAL knockdown." (PMID 40713894, 2025).
gastric tumors (1 paper, 2021). "In keeping with mRNA expression, TTPAL protein expression was also significantly higher in primary gastric tumors as compared to adjacent non-tumor tissues by immunohistochemical (IHC) staining (N = 86, p < 0.0001)." (PMID 34642500, 2021).
metastatic tumors (1 paper, 2021). "The protein expression of Ki64, NNMT, and p-AKT was also increased in TTPAL-overexpressed metastatic tumors validating that TTPAL promoted gastric metastasis by inducing NNMT and activating PI3K/AKT signaling." (PMID 34642500, 2021).
osteoporosis (1 paper, 2024). A condition of reduced bone mass, with decreased cortical thickness and a decrease in the number and size of the trabeculae of cancellous bone (but normal chemical composition), resulting in increased fracture incidence. "Specifically, the identification of PTBP1, H2AFZ, BCL6, and TTPAL as the regulators of osteogenic differentiation presents novel therapeutic targets for conditions such as osteoporosis and bone fracture healing." (PMID 39766835, 2024).
tumor (5 papers, 2014 to 2025). "First, the correlation between increased TTPAL DNA copy number and its expression requires further validation through additional patient specimens and analysis in other tumor tissues." (PMID 40713894, 2025). "SREBP2 and NSUN2 expression levels exhibited significant positive correlations with TTPAL tumor expression." (PMID 40713894, 2025). "We establish that TTPAL promotes tumor initiation and progression through m5C-mediated stabilization of SREBP2 mRNA, executed via its interaction with the methyltransferase NSUN2." (PMID 40713894, 2025). "Pan-cancer analysis confirmed strong positive correlations between TTPAL expression and cholesterol biosynthetic enzyme levels across tumor types." (PMID 40713894, 2025). "Alteration of mRNA levels of CDH1, FHIT, PTEN, and TTPAL genes in tumor tissues was determined compared to control tissues." (PMID 36161592, 2022). "While the mRNA levels of CDH1 decreased, the mRNA level of the FHIT and TTPAL genes increased in the tumor tissues." (PMID 36161592, 2022). "In accordance with in vitro findings, TTPAL promoted tumor growth in mouse subcutaneous xenograft models and promoted lung metastasis in tail vein injection mouse models." (PMID 34642500, 2021). "Ectopic expression of TTPAL promoted GC cell proliferation, migration, and invasion in vitro and promoted murine xenograft tumor growth and lung metastasis in vivo." (PMID 34642500, 2021). "TTPAL markedly promoted the growth of tumor volume and increased tumor weight in subcutaneous xenograft models." (PMID 34642500, 2021). "The PCR array result showed, ectopic expression of TTPAL activated the expression of PI3K/AKT signaling-related genes while downregulated tumor suppressors, such as RBL2, PTEN, and CDKN1B (p27)." (PMID 34642500, 2021). "Moreover, inhibition of cholesterol biosynthesis led to tumor suppression in ESCC cells with high TTPAL expression, offering a potential strategy for ESCC treatment." (PMID 40713894, 2025). "Moreover, after stratified by tumor staging, TTPAL overexpression predicted poor prognosis in stages I–III GC patients, but not for stage IV GC patients." (PMID 34642500, 2021). "Using Ttpal-KO mouse mode, we demonstrate that TTPAL promotes ESCC cell proliferation and accelerates tumor development by driving cholesterol biosynthesis." (PMID 40713894, 2025). "Based on these in vitro findings, we used subcutaneous xenograft mouse models and found that TTPAL knockdown in ESCC cells markedly inhibited the increase of tumor volume over the entire assay period, leading to a decrease in the final tumor weight." (PMID 40713894, 2025). "Our investigation establishes that TTPAL expression in ESCC directly correlates with its genomic amplification status, with significant overexpression observed in primary tumor specimens relative to matched normal epithelium." (PMID 40713894, 2025). "We analysed the expression of mRNAs for CDH1, PTEN, FHIT, and TTPAL by real-time PCR and observed downregulation of CDH1 and upregulation of FHIT and TTPAL in the tumor tissues." (PMID 36161592, 2022).
cancer (4 papers, 2021 to 2025). A tumor composed of atypical neoplastic, often pleomorphic cells that invade other tissues. "Originally characterized as a putative phosphatidylinositol bisphosphate-binding protein, TTPAL has recently been implicated in cancer biology through distinct mechanisms." (PMID 40713894, 2025). "High TTPAL expression predicted a higher risk of cancer-related death by univariate Cox regression analysis (relative risk (RR) = 1.832, 95% CI: 1.075–3.122, p = 0.026)." (PMID 34642500, 2021). "In TCGA dataset, the expression of TTPAL mRNA was positively correlated with the expression levels of SREBP2 mRNA and its downstream target genes in different types of cancers." (PMID 40713894, 2025).
TTPAL also shares sentences with these, for which no sentence is quoted: colon cancer (1 paper); colorectal tumors (1); esophageal squamous cell carcinoma (1); lung carcinoma (1).